BRAF (B-Raf proto-oncogene, serine/threonine kinase)
Diseases named in the same sentence as BRAF in open-access papers (continued):
Sharing a sentence is not in itself a finding about the gene and the disease.
tumor (continued). "Patient sex, age, TNM stage, tumor location, treatment methods, histology, KRAS mutation, BRAF mutation, Fusobacterium nucleatum, mucin phenotype, and programmed death-ligand 1 (PD-L1) status were evaluated." (PMID 34797780, 2021). "A phase II study stratified patients by BRAF aberration status, histological diagnosis, tumor location, and NF-1 status." (PMID 32375301, 2020). "While dabrafenib usually inhibits the proliferation of cancer cells by targeting BRAFV600E, it was also shown to induce the proliferation of tumor cell lines expressing wild-type BRAF and mutant RAS." (PMID 32650447, 2020). "BRAF, NRAS, and TERT somatic mutations were evaluated in patient’s tumor tissue as part of clinical routine." (PMID 33122747, 2020). "Tumour analyses within cohorts treated with BRAF inhibiting monotherapies suggest a prevalence of approximately 30% for splicing variants." (PMID 33216826, 2020). "The CIMP pathway, reported in the 20-30% of sporadic CRC, involves the serrated neoplasia pathway and mutations in KRAS 10% (usually B-Raf proto-oncogene serine/threonine kinase—BRAF—wild type) and BRAF~70%." (PMID 32676506, 2020). "TGF-beta signaling is known to have a tumor suppressive effect in skin stem cells and loss of TGF-beta signaling has been associated with SCC development in adults treated with BRAF inhibitors." (PMID 32523649, 2020). "We identified a BRAF(V600E) mutation and a TERT promoter mutation in the PF49 tumor cells and found that these mutations were already present in the primary PTC." (PMID 32591993, 2020). "Out-patient orders to check the tumor’s BRAF and programmed death-ligand 1 status, as well as assess for other tumor markers were placed." (PMID 32724562, 2020). "More importantly, the patient-derived tumor xenografts (PDXs) model revealed that co-inhibition of BRAF and FAK abolishes ERK reactivation in tumor stroma." (PMID 32278350, 2020). "The cultures presented a range of patient-specific morphologies and well represented the morphologies and genetic landscape (i.e., KRAS and BRAF mutations and MSI status) of primary tumor specimens." (PMID 32290033, 2020). "The activation of oncogenes, such as Ras or B-Raf proto-oncogene, serine/threonine kinase (BRAF), or the inactivation of tumor suppressors, such as PTEN, will result in OIS." (PMID 32215170, 2020). "Recent studies have indicated that the effect of the BRAF V600E mutation for PTC recurrence would be minimized, or even be protective, after adjustment of possible confounders including age, sex, tumor size, and multifocality." (PMID 32722429, 2020). "Females also present with a higher incidence of BRAF mutations associated with sporadic MSI cancers as a consequence of age-related enhanced levels of DNA methylation and silencing of tumor-suppressor genes responsible for oncogene-induced senescence." (PMID 32512823, 2020). "Additional genetic testing revealed the patient was negative for EGFR, ALK fluorescence in situ hybridization, ROS1, BRAF, and PD-L1 22C3 IHC with Tumor Proportion Score (TPS) was less than 1%." (PMID 33101670, 2020).
tumor (continued). "Among the baseline characteristics, age, tumor stage, tumor site, MSI-H phenotype, BRAF mutation, and PIK3CA mutation were significantly different across the four clusters and were adjusted in the following survival analysis." (PMID 33163194, 2020). "Studies of the association between BMI and molecular subtypes of CRC defined by key molecular tumor features such as KRAS and BRAF mutation status or MSI status have been inconclusive." (PMID 32210264, 2020). "Nevertheless, targeted tumor therapies can be restricted by the emergence of resistant tumor cells to BRAF inhibitors and EGFR inhibitors." (PMID 32695658, 2020). "In this study, all tumor tissue samples from the considered patients were retrieved from the pathology department and tested for RAS/BRAF mutation status, which was matched between the two groups after PSM." (PMID 33099304, 2020). "This study analyzed clinicopathological data of patients affected with any stage TCC and identify tumor grade and BRAF status as independent prognostic factors for survival." (PMID 32872561, 2020). "The anti-tumor effects of these BRAF inhibitors are enhanced by co-administration of MEK inhibitors." (PMID 32626712, 2020). "Although the concordance between matched ctDNA and archival tumor tissue was high for selected ‘hot-spot’ mutations (KRAS, BRAF, PIK3CA), some differences were noted between archival tumor and ctDNA." (PMID 32010431, 2020). "BRAF inhibitor-resistant tumor cells also show reduced expression of target antigens, and increased production of IL-10." (PMID 33003483, 2020). "Compared to the low-immunity group, the high-immunity group exhibited more advanced stages, larger tumor sizes, greater lymph node metastases, higher tall-cell PTCs, lower follicular PTC proportions, more BRAF mutations, and fewer RAS mutations." (PMID 33193087, 2020). "BRAF+ tumours had upregulated genes involved in angiogenesis, cell death and metabolism, but down-regulated genes associated with proliferation, cell cycle and inflammation." (PMID 32843682, 2020). "For patients with CDX2 status available, 21% had a BRAF V600E mutation (BRAFmut), 41% a KRAS mutation (KRASmut), 8% were MSI high (MSI-H), and 38% double (KRAS and BRAF) wild-type tumor." (PMID 32117703, 2020). "Consistently, a tissue analysis revealed that forced miR-146a expression remarkably reduced tumor cell proliferation in 3D cultured explants upon BRAF/MEKi treatment." (PMID 32967672, 2020). "BRAF-mutant tumours create an immunosuppressive microenvironment that prevents the presentation of tumour antigens by antigen-presenting cells (such as dendritic cells and macrophages), and the T-cell priming that follows." (PMID 32645969, 2020). "This is supported by our previous results that showed high concordance between preoperative BRAF mutation analysis from FNAB specimens and postoperative from the primary tumor." (PMID 33247684, 2020). "Detection of BRAFV600E within cell free tumor DNA (ctDNA) is emerging as a promising means to improve patients’ stratification or enable BRAF inhibitor (BRAFi) therapeutic monitoring in a minimally invasive manner." (PMID 32978468, 2020). "Previous studies have shown that Cu influx via the Cu-importer CTR1 plays a crucial role in mutant BRAF-driven tumor growth." (PMID 32709883, 2020). "In 5/17 (29%) cases, we observed the coincident BRAF, KRAS and NRAS mutations in cfDNA matched bone marrow tumor DNA." (PMID 32284750, 2020). "Unsupervised hierarchical analysis at the family level revealed a characteristic “healthy” microbial signature in controls segregated from that one of CRC-bearing mice, being BRAFV600E CRCs closer to tumor-free mice than BRAF wt tumors." (PMID 33317591, 2020). "Within these eleven studies, analysis of tumor mutational events varied from driver gene genotyping of KRAS, BRAF, and/or NRAS, to analysis of the genome-wide mutational spectrum of the tumor." (PMID 33228212, 2020).
tumor (continued). "In our study, the positive BRAF, KRAS and NRAS mutations in the bone marrow tumor DNA samples were 28/83 (34%), but it was 9/17 (53%) in the plasma cfDNA samples, which demonstrated a significantly higher detection rate." (PMID 32284750, 2020). "TAMs induce resistance to MAPK inhibitors by favoring the expression of tumor resistance factors or through their direct paradoxical activation of the pathway, driven by BRAF inhibitors." (PMID 33036192, 2020). "However, a few tumours with RAS or BRAF V600E mutations may have been included." (PMID 32863385, 2020). "Poorly differentiated tumor was significantly associated with advanced age (p = 0.005), poor ECOG PS (p = 0.004), lympho-vascular/perineural invasion (p = 0.042) and BRAF status (p = 0.003)." (PMID 32872561, 2020). "Considering that dynamic, we aimed to determine how v-raf murine sarcoma viral oncogene homolog B1 (BRAF) V600E and Kirsten rat sarcoma (KRAS) mutations relate to the location, histopathology, and degree of tumor differentiation in CRC." (PMID 33145020, 2020). "It was observed that BRAF inhibitors do not only act on tumor cells but also on the neighboring tumor fibroblasts, paradoxically activating them to produce a stiff, collagen‐rich ECM." (PMID 32749065, 2020). "The BRAF driver mutation causes the constitutive activation of the MAPK pathway with loss of differentiation, tumor progression and apoptosis inhibition." (PMID 33986723, 2020). "Nano-construct modified with the galactose-targeting moieties resulted in high accumulation of GAL-GNR-siBRAF in tumor cells, inducing effective downregulation of BRAF gene expression." (PMID 32449085, 2020). "For example, the right hemicolon tumor is generally poorly differentiated, displaying different molecular patterns, higher BRAF mutation, and MSI-high phenotype than the left hemicolon tumor." (PMID 32509862, 2020). "BRAF+ tumours were found to have significantly increased levels of peritumoural and intratumoural iNOS+ cells." (PMID 32843682, 2020). "Evaluation of plasma from patients with reported objective response to BRAF/MEK inhibition followed by disease progression was revealed by increased circulating tumour DNA (ctDNA) in 24 of 38 cases at the time of relapse." (PMID 33216826, 2020). "This led to the combination of PD-L1 and BRAF inhibition in a murine model, showing again a shrinkage in tumor volume." (PMID 32668761, 2020). "In summary, the molecular analysis of a small amount of unamplified cfDNA for BRAF, KRAS and NRAS mutations in MM patients is feasible and has good concordance with standard mutations testing of bone marrow tumor DNA samples." (PMID 32284750, 2020). "Of note, in this study, the BRAF mutant group includes tumors either directly confirmed for the BRAF V600E mutation by IHC or NGS, or tumor histologies where BRAF mutations are frequent (eg, JPA)." (PMID 32642706, 2020). "This trial delineates the contribution of tumor response attributable to the use of a BRAF inhibitors and not only because of the re-use of RAI." (PMID 32668761, 2020). "Surprisingly, phendione treatment was significantly more effective in reducing tumor growth than the BRAF inhibitor." (PMID 32241802, 2020). "Within few months after inhibition of BRAF, several mechanisms allow the tumor to overcome this block and patients develop resistance to BRAF inhibitors." (PMID 33292371, 2020). "Molecular analysis revealed that the tumor harbored ALK rearrangement and BRAF mutations simultaneously." (PMID 32991441, 2020). "Previous report confirmed that AZD8055 exhibited an obvious tumor-inhibition effect in HRAS mutant or BRAF mutant PTC cells induced xenograft models." (PMID 32284745, 2020).
tumor (continued). "Among these, CMS1 (microsatellite instability immune) tumors are associated with poorer prognosis, high tumor mutational load, MSI, CIMP, BRAF mutation, female gender and right-sided location." (PMID 32183342, 2020). "BRAF mutated tumours showed higher fractions of PD-1+ T cells, B cells and CD163+ macrophages compared to BRAF wild type tumours." (PMID 33228141, 2020). "ERK1/2 promotes cell survival in BRAF- or KRAS-mutant tumor cells by increasing the expression of pro-survival BCL-2 proteins and further stabilizes the MCL-1 protein." (PMID 33308268, 2020). "The presence of other molecular abnormalities, such as EGFR, KRAS, BRAF or HER2 mutations and ALK rearrangements, has also been identified in some of these tumours." (PMID 31598903, 2020). "This selective MEK1/2 inhibitor is a benzoxazole compound with high potency and exhibits anti-tumor activity in BRAF- and NRAS-mutant tumor cell lines." (PMID 32092958, 2020). "Further, A2AR-deficient NK cells were found to have enhanced maturation, maintain a proliferative advantage over wildtype NK cells, and protect against tumor development in a transplantable BRAF-melanoma tumor model." (PMID 33613552, 2020). "Selected treatment options are now dependent on a range of factors including stage, patients’ health status, initial treatment intent (curative vs. palliative), clinical features such as tumor location and molecular factors (e.g., RAS, BRAF mutational status)." (PMID 32231042, 2020). "We also find that NGFRhi tumor cells are cross-resistant to BRAF (+MEK) inhibition, thereby corroborating other recent (single cell) approaches and extending previous RNA profiles suggesting co-evolution of MAPKi resistance and CD8 T cell exhaustion." (PMID 32770055, 2020). "Based on genetic analyses, cutaneous melanomas are divided into four classes: BRAF-mutated, RAS-mutated, NF-1-mutated tumours, and triple wild-type." (PMID 31599373, 2020). "Oncogenic BRAF, through decreased MITF expression and enhanced IL-1α and IL-1β secretion, triggers PD-L1 and PD-L2 expression in tumor-associated fibroblasts which also contributes to suppression of tumor-infiltrating T cell function." (PMID 33276788, 2020). "Additional, ongoing studies are being performed to investigate how some of these BRAF inhibitors work in combination with other therapies to promote a synergistic, anti-tumor effect in NSCLC patients." (PMID 33182254, 2020). "Collectively, these findings corroborated with previous reports illustrating the association of PTEN (PTEN: tumor suppressor and PI3K antagonist) with PI3K/Akt activation and resistance to BRAF inhibitors." (PMID 32899183, 2020). "Tumor aA_7 exhibited multiple losses of chromosomal regions, homozygous deletion of CDKN2A/B and a particular mutation of BRAF (p.D594G) by NGS analysis." (PMID 32758285, 2020). "To confirm our findings in patients, we performed immunohistochemical analysis of COX2 and pERK expression, and genotyping of the BRAF gene using the clinical tumour tissues from cUC patients." (PMID 32385388, 2020). "A significant relationship exists between BRAF V600E mutations in the stool of patients with CRC and the tumor location, histopathology, and degree of tumor differentiation." (PMID 33145020, 2020). "A transient benefit from treatment with anti-EGFR targeted therapies initially occurs due to bulk killing of drug-sensitive RAS/BRAF wt cells and consequent measurable tumor volume reduction." (PMID 32183295, 2020). "Tissue immunostaining confirmed higher COX2 expression in tumor lesions progressing during BRAF/MEKi therapy compared to matched pretreatment lesions in 3 out of 7 tested cases." (PMID 32967672, 2020). "A significant relationship exists between BRAF V600E mutations in the stool of patients with CRC and location, histopathology, and degree of tumor differentiation." (PMID 33145020, 2020).
tumor (continued). "By comparing the matching tumor derived organoids and primary tumors, we found that the organoids well represented the morphologies and genetic landscape (KRAS, BRAF, mutation and MSI) of the corresponding primary tumor specimens." (PMID 32290033, 2020). "Within the mTOR pathway of subtype-1 tumours, we found increased expression of well-documented oncoproteins including MTOR and BRAF: both of which have previously been linked to pancreatic carcinogenesis 25–27." (PMID 31988390, 2020). "For example, a BRAF inhibitor, when combined with an anti-PD-1 or anti-PD-L1 antibody, can increase the number and activity of tumor-infiltrating lymphocytes (TILs) in melanoma, leading to improved tumor control and patient survival." (PMID 32929370, 2020). "In around 30% of resistant tumours, resistance to BRAF inhibition is conferred by alternative splicing via generation of BRAF isoforms lacking the RAS binding domain (RBD) encoded by exons 3–5." (PMID 33216826, 2020). "In the immunotherapy cohort, 30 patients were BRAF mutant (42%), 20 were NRAS mutant (28%) and 22 patients had other driver mutations that were used to track the tumour." (PMID 33339135, 2020). "In 90% of these tumours, mutations in the MAPK pathway are found, with BRAF V600E being the most common mutation, whilst outside the MAPK pathway SMO mutation is the most frequently referenced." (PMID 32388513, 2020). "75% of these tumor samples showed ≥1 (likely) pathogenic mutation, including targetable mutations (e.g. EGFR, BRAF, MET, ERBB2, KIT, PDGFRA)." (PMID 32264863, 2020). "Further, an increased infiltration of CD8+ T cells into the tumor was observed after BRAF inhibition which is accompanied by an increased PD-L1 expression." (PMID 31541179, 2020). "We present the outcomes of a case series of 13 patients who achieved complete tumour response following BRAF inhibitor monotherapy or combination BRAF/MEK inhibition, and ceased therapy for observation after maintaining sustained remission." (PMID 33139839, 2020). "Once BRAF inhibitor resistance develops, the tumor microenvironment reverts to a low immunogenic state secondary to the induction of programmed cell death ligand-1." (PMID 33003483, 2020). "To explore the early events associated with the development of PTC, we used massively parallel sequencing to investigate BRAF exon 15 in 30 PTCs and in 100 samples from the thyroid parenchyma surrounding the tumor." (PMID 32059434, 2020). "However, the concordance rate of KRAS and BRAF mutation analysis was 94% and 100% in a previous report, suggesting only a marginal influence of whether the sample for mutation analysis is taken from the primary tumor or the metastasis." (PMID 31571052, 2020). "Analysis of serine/threonine-protein kinase B-raf (BRAF) gene mutations displayed wild type alleles of BRAF for exon 11 and 15 for both parental tumor tissue and isolated BKZ-2 and BKZ-3 cells." (PMID 32927768, 2020). "The decision model describes the influence of pT stage, number of lymph nodes evaluated, tumor sidedness, MSS status, BRAF mutation status, and KRAS mutation status on relevant outcomes, such as the recurrence rate and disease-specific survival." (PMID 32458162, 2020). "The organoid cultures well represented the morphologies and genetic landscape (i.e., KRAS and BRAF mutations and MSI status) of the primary tumor specimens." (PMID 32290033, 2020). "In this study, we used CRISPR-Cas9 technology to edit the BRAF V600E gene and found a good inhibitory effect on tumor cells." (PMID 33330635, 2020).